MAD2L1 (mitotic arrest deficient 2 like 1)
Description:
Component of the mitotic checkpoint complex (MCC), which inhibits APC/C and delays chromosome segregation until all chromosomes are properly attached to the mitotic spindle. The MCC, which consists of CDC20, MAD2L1/MAD2, BUB1B/BUBR1 and BUB3, is a key player of the spindle assembly checkpoint. The MCC-bound APC/C complex is inactive and this delays the metaphase/anaphase transition. When the spindle assembly checkpoint is silenced, the MCC-APC/C complex recruits the E2 enzyme UBCH10 and triggers the auto-ubiquitination of CDC20 in the MCC, thereby reactivating APC/C for transition into anaphase. In the closed conformation (C-MAD2) forms a heterotetrameric complex with MAD1L1 at unattached kinetochores during prometaphase, the complex recruits open conformation molecules of MAD2L1 (O-MAD2) and then promotes the conversion of O-MAD2 to C-MAD2.
Synonyms: HsMAD2; MAD2
Tractability: Small molecule: a structure with a bound ligand is known; it has a high-quality binding pocket. PROTAC: ubiquitination databases record sites on it; its protein half-life has been measured.
Gene: Protein-coding gene on chromosome 4 (120,055,623 to 120,067,192, reverse strand). Ensembl gene ENSG00000164109.
Subcellular location: Nucleus; Chromosome, centromere, kinetochore; Cytoplasm; Cytoplasm, cytoskeleton, spindle pole
Subcellular location (Human Protein Atlas): Nucleoplasm
Pathways (Reactome):
Cell Cycle: APC-Cdc20 mediated degradation of Nek2A; APC/C:Cdc20 mediated degradation of mitotic proteins; Amplification of signal from unattached kinetochores via a MAD2 inhibitory signal; Cdc20:Phospho-APC/C mediated degradation of Cyclin A; EML4 and NUDC in mitotic spindle formation; Inactivation of APC/C via direct inhibition of the APC/C complex; Inhibition of the proteolytic activity of APC/C required for the onset of anaphase by mitotic spindle checkpoint components; Mitotic Prometaphase; Resolution of Sister Chromatid Cohesion; Separation of Sister Chromatids
Signal Transduction: RHO GTPases Activate Formins
Gene Ontology:
Molecular function: identical protein binding; protein binding; protein homodimerization activity
Biological process: mitotic spindle assembly checkpoint signaling; negative regulation of mitotic cell cycle; negative regulation of protein catabolic process; negative regulation of ubiquitin protein ligase activity; positive regulation of mitotic cell cycle spindle assembly checkpoint; negative regulation of mitotic cell cycle phase transition; regulation of nuclear division
Cellular component: cytoplasm; cytosol; kinetochore; mitotic checkpoint complex; mitotic spindle; mitotic spindle assembly checkpoint MAD1-MAD2 complex; nuclear pore nuclear basket; nucleus; perinuclear region of cytoplasm; chromosome; chromosome, centromeric region; spindle pole
Genetic constraint (gnomAD): Loss-of-function variants: 8 observed, 21.09 expected, observed/expected ratio (o/e) 0.38, 90% interval 0.22 to 0.68. The upper end of that interval is the gene's LOEUF score, 0.68, which puts it in group 2 of 6, group 1 being the genes least tolerant of losing a copy. Missense variants: 150 observed, 208.89 expected, observed/expected ratio (o/e) 0.72, 90% interval 0.63 to 0.82. Synonymous variants: 71 observed, 73.82 expected, observed/expected ratio (o/e) 0.96, 90% interval 0.79 to 1.17.
Homologues: Orthologues: chimpanzee MAD2L1 (100% identical), macaque MAD2L1 (100% identical), pig MAD2L1 (99% identical), rabbit MAD2L1 (98% identical), guinea pig MAD2L1 (97% identical), mouse Mad2l1 (94% identical), rat Mad2l1 (94% identical), zebrafish mad2l1 (74% identical), Caenorhabditis elegans mdf-2 (50% identical), Drosophila melanogaster mad2 (44% identical). Paralogues in human: MAD2L2 (26% identical).
Diseases named in the same sentence as MAD2L1 in open-access papers:
MAD2L1 is named in the same sentence as 79 diseases in open-access papers, as found by Europe PMC text mining. Sharing a sentence is not in itself a finding about the gene and the disease. The quoted sentences say what the papers report.
breast carcinoma (33 papers, 2006 to 2026). "MAD2L1 is a component of the mitotic spindle assembly checkpoint that has been linked to early metastasis in breast cancer and is associated with BRCA1/2 pathogenic mutations." (PMID 36860495, 2022). "MAD2L1 has been documented to be associated with female breast cancer, where it is usually deleted or amplified simultaneously with BUB1B." (PMID 35132379, 2022). "Studies showed that MAD2L1 presented overexpression in breast cancer and was significantly associated with higher clinical stage, higher histological grade, aggressive tumors, and worse disease-free survival." (PMID 33133141, 2020). "Using the gene expression data from our microarray analysis of breast cancer, we examined the associations of MAD2L1 and BUB1 expression with tumor features and disease outcomes." (PMID 26287798, 2015). "In our study of microarray expression data from 203 breast cancer patients, we analyzed the genes present in multiple signatures, and found three genes (MAD2L1, PTTG1 and BUB1) significantly associated with disease-free or overall survival." (PMID 26287798, 2015). "Our investigation showed that high MAD2L1 or BUB1 expression was associated with poor prognosis of breast cancer, and moreover in vitro suppression of their expression resulted in reduced cell proliferation and less aggressive cell behavior." (PMID 26287798, 2015). "Among the larger modules, we identified one associated with the cell-cycle (CDC2, CDC20, MYBL2, MAD2L1) consistent with many other studies showing the importance of cell-cycle genes in breast cancer prognosis." (PMID 20673354, 2010). "This may highlight the potential of MAD2L1 to act as a possible therapeutic target not only in BRCA1/2-mutated breast cancer but also in a wider group of patients with a high activity level of this pathway." (PMID 32620799, 2020). "In addition, overexpression of BUB1 and the MAD2 related protein MAD2L1 is associated with aggressive tumors in breast cancer, suggesting that dysregulation of SAC signaling may be involved in chromosome instability and aneuploidy." (PMID 33717411, 2021). "In summary, these results indicate that RCC2, as a lactylation substrate, regulates the MAD2L1 pathway and promotes breast cancer proliferation in a high lactate environment." (PMID 40145796, 2025). "The lactylation of RCC2 mediates the activation of the cellular MAD2L1 signaling pathway and contributes to the progression of breast cancer." (PMID 40145796, 2025). "We found a significant correlation between the expression of RCC2 and MAD2L1 in breast cancer (R = 0.54)." (PMID 40145796, 2025). "Collectively, these results demonstrate that high‐glucose conditions promote lactate accumulation, which drives proliferative activation in breast cancer via MAD2L1 upregulation." (PMID 40145796, 2025). "The pathological significance of MAD2L1 in breast cancer; the metastasis promotion of PITPNC1 by melanoma, breast cancer, and colon cancer cells; and the suppression of breast tumors by RIN1 have also been reported." (PMID 33519944, 2021). "MAD2L1 is overexpressed in multiple cancerous, such as breast cancer and gastric cancer, and lung cancer." (PMID 33186389, 2020). "Pathway activity levels are found to be strong predictive biomarkers for the essentiality of 15 proteins, including the essentiality of MAD2L1 in breast cancer patients with high BRCA-pathway activity." (PMID 32620799, 2020). "Among patients with primary breast cancer, higher expression of MAD2L1 and BUB1 existed in patients with ER-, PR-, and high-grade tumors compared to those with ER +, PR+, and low-grade tumors." (PMID 31777591, 2019). "Overexpression of MAD2L1 and BUB1, candidate hub genes in our study, has previously been associated with high grade breast tumors and poor survival of breast cancer patients." (PMID 29088818, 2017). "We and others found high expression of MAD2L1 and BUB1 in breast cancer and their associations with unfavorable prognosis." (PMID 26287798, 2015).
breast carcinoma (continued). "Associations of MAD2L1 and BUB1 expression with clinical and molecular characteristics of breast cancer." (PMID 26287798, 2015). "SERBP1 can prevent the degradation of MAD2L1 mRNA (the degradation rate decreases by 40%), leading to the up-regulation of MAD2L1 protein expression, which in turn activates the cell cycle checkpoint and promotes the rapid proliferation of breast cancer cells." (PMID 41227349, 2025). "In addition to regulating MAD2L1 mRNA stability in breast cancer (as mentioned in Section 4.3), it can also interact with Cyclin B1 mRNA in oocytes and tumor cells." (PMID 41227349, 2025). "Given that RCC2 lactylation activates the MAD2L1 pathway and promotes breast cancer cell proliferation, it may represent a promising therapeutic target." (PMID 40145796, 2025). "Elevated expression levels of RCC2, SERBP1, and MAD2L1 were positively correlated with poor prognosis and shorter survival times in breast cancer patients, suggesting that they may serve as biomarkers for clinical prognosis assessment." (PMID 40145796, 2025). "MAD2L1 has been shown high expression levels and might be a biomaker for poor prognosis in various cancers, such as breast cancer, osteosarcoma (Sun, Li & Yan, 2015), and so on." (PMID 32411535, 2020). "MAD2L1 may have great effect on breast cancer progression, and its expression might help to predict breast cancer prognosis." (PMID 32461838, 2020). "Interestingly, a majority of Survivin interacting molecules that were found to be significantly regulated by Pirfenidone are also associated with the mitotic spindle (MAD2L1, BUB1, BUB1B, BUB3, CDC20) and were shown to be increased in human breast cancer." (PMID 32039023, 2019). "It is reported that measuring the expression of MAD2L1 may assist the prediction of breast cancer prognosis." (PMID 29467930, 2018). "The potential mechanisms of MAD2L1 in breast cancer require further investigation." (PMID 29467930, 2018). "MAD2L1 is a component of the mitotic spindle assembly checkpoint, and it may play crucial roles in the progression of breast cancer." (PMID 29467930, 2018). "We further investigated the associations of MAD2L1 and BUB1 expression with breast cancer survival." (PMID 26287798, 2015). "Taken together, these results suggest that low MAD2L1 or BUB1 expression may inhibit breast cancer cell proliferation, invasion, and migration." (PMID 26287798, 2015). "In addition, integrating pathway and gene information, we identified five (ID4, ANXA4, CXCL9, MYLK, FBXL7) and six (SQLE, E2F1, PTTG1, TSTA3, BUB1B, MAD2L1) known cancer genes significant for ovarian and breast cancer respectively." (PMID 22759382, 2012). "Besides, overexpression of MAD2L1 leads to chromosomal instability in lung tumour cells, and is highly correlated with high levels of BRCA pathway activity and BRCA1/2 pathogenic mutations in breast cancer patients." (PMID 37469408, 2023). "In breast cancer, KAT2A‐mediated RCC2 lactylation at K124 facilitates RCC2 recruitment of SERBP1, stabilizing MAD2L1 mRNA and promoting progression." (PMID 41454479, 2026). "High expression of MAD2L1, CCNA2 and FUT8-AS1 and low expressions of LINC01279, RAD51-AS1 and CARMN were correlated with significantly worse OS in breast cancer patients, while Other candidate hub genes expression were not significantly relevant to OS." (PMID 33128008, 2020). "Breast cancers and breast cancer cell lines overexpress several mitotic regulators, including kinases that regulate the SAC such as Nek2, Mad1L1, Mad2L1, Mad2L2, BubR1, BubR1B, Bub3, Cdc20, and Mps1/TTK." (PMID 29100415, 2017). "In summary, our study confirmed the prognostic value of two key mitotic checkpoint genes MAD2L1 and BUB1, which have been included in multiple gene expression signatures for breast cancer prognosis." (PMID 26287798, 2015). "In the TCGA breast cancer cohort, RCC2 was identified as a gene co‐expressed with MAD2L1." (PMID 40145796, 2025).
breast carcinoma (continued). "CALCR (coding calcitonin receptor) has similar gene expression patterns to MAD2L1 and RSL1D1 in tamoxifen-resistant MCF7 cells; the expression of these genes was all correlated with worse RFS in ER-positive/HER2-negative breast cancer patients who had undergone endocrine therapies only." (PMID 33133141, 2020). "Our investigation suggests that MAD2L1 and BUB1 may play important roles in breast cancer progression, and measuring the expression of these genes may assist the prediction of breast cancer prognosis." (PMID 26287798, 2015). "Collectively, all of these observations suggest that MAD2L1 and BUB1, two genes present in multiple gene expression signatures for breast cancer prognosis, may be important molecules influencing tumor cell activity and patient survival." (PMID 26287798, 2015). "Therefore, MAD2L1, RSL1D1, and CALCR might be promising candidates for further research in endocrine therapy-resistant breast cancer as potential therapeutic targets or prognostic markers." (PMID 33133141, 2020). "Notably, in dataset GSE202923, breast cancer cells HS578T cultured in low‐glucose conditions exhibited a significant downregulation of MAD2L1, suggesting that glucose metabolism may influence the MAD2L1 signaling pathway in tumor cells." (PMID 40145796, 2025). "Our analysis of MAD2L1 and BUB1 in two datasets (GSE37751 and GSE29044) also demonstrated higher expression in breast cancer than in adjacent non-tumor tissues." (PMID 26287798, 2015).
lung carcinoma (17 papers, 2012 to 2026). "The Leu84Met SNP of MAD2L1 has an increased related risk to progress into lung cancer depending on the allele dose." (PMID 36101460, 2022). "Overexpression of MAD2L1 can lead to lung carcinoma susceptibility." (PMID 35918384, 2022). "In mouse models, deletion of the MAD2L1 gene can cause liver and lung cancer." (PMID 35037540, 2022). "Our study has shown that suppression of miR-195-5p/-3p expression and overexpression of the ANLN/MAD2L1 genes are among the factors that accelerate the progression of lung cancer cells." (PMID 40723231, 2025). "More recently, it has been reported that MAD2L1 expression is involved in carboplatin resistance in lung cancer cells." (PMID 40723231, 2025). "This is a low minor allele frequency (MAF) based on the NCBI database [A = 0.000004/1 (GnomA Dexomes)], but some investigators have found a polymorphism of MAD2L1 rs1283639804 in combination with the polymorphism of MAD1L1 rs1801368 conferring colorectal and lung cancers." (PMID 37007941, 2023). "Some studies reported that MAD2L1 and CCNB2 are highly expressed in gastric cancer, liver cancer, lung cancer, and other types of cancers; thus, they possibly serve as tumour-promoting genes, which are consistent with our immunohistochemical results." (PMID 34838000, 2021). "The result revealed an really interesting fact that even in different sub types of lung cancer (LUAD and LUSC), NDC80 and MAD2L1 shared biological functions." (PMID 32795325, 2020). "A signature of genes including CDC20, CCNB1, CDC2, CDKN3, MAD2L1, PRC1 and RRM2, were prognostic for 5-year survival in over 400 lung cancer cases, and interestingly, CDC20, CDC2, CCNB1 were also highly overexpressed in the aggressive case." (PMID 22905093, 2012). "Also specific to the epithelial compartment, we observed enrichment for a signature conferring poor outcome in lung cancer, which included general cancer prognostic genes like AURKB, EXO1, MAD2L1, CDCA8, and kinesins like KIF15." (PMID 32883324, 2020).
colorectal cancer (14 papers, 2007 to 2026). A primary or metastatic malignant neoplasm that affects the colon or rectum. "For CRC, the higher expression of MAD2L1 has been observed to counteract the repressive impact of miR-515-5p overexpression on the proliferation of colorectal cancer cells, as well as the induction of apoptosis and G1-phase detainment." (PMID 37383715, 2023). "MAD2L1 can regulate the growth and apoptosis of colorectal cancer cells." (PMID 34838000, 2021). "The core genes, namely MYC, MAD2L1, CENPF, UBE2C, NUF2 and NCAPG2, showed elevated expression in colorectal cancer samples, in stark contrast to their comparatively lower expression in normal samples." (PMID 38637125, 2024). "In particular, MYC, MAD2L1, CENPF, UBE2C, NUF2 and NCAPG2 were identified as highly expressed in colorectal cancer samples." (PMID 38637125, 2024). "CCNA2, MAD2L1, DLGAP5, and RRM2 were all significantly related to the pathological stages of colorectal cancer and were also closely related to the stage of lymph node metastasis." (PMID 33519906, 2020). "Notably, the core genes (MYC, MAD2L1, CENPF, UBE2C, NUF2, NCAPG2) had differential expression in colorectal cancer samples in comparison to normal samples." (PMID 38637125, 2024). "Among them, we found that CCNA2, MAD2L1, DLGAP5, and AURKA were related to the overall survival (OS) of colorectal tumors, while RRM2 and AURKA had the relation between disease-free survival (DFS) and colorectal cancer." (PMID 33519906, 2020). "However, consistent with experimental data, colorectal cancers showed a moderate negative correlation between Twist1 and MAD2L1—a mitotic spindle assembly checkpoint protein." (PMID 32337580, 2020).
gastric cancer (14 papers, 2007 to 2025). A primary or metastatic malignant neoplasm involving the stomach. "As a pro-oncogene upregulated in gastric cancer, MAD2L1 (mitotic arrest deficient 2-like protein 1) can be downregulated expression by miR-30a-3p, resulting in inhibition of the proliferation of gastric cancer cells." (PMID 33767726, 2021). "MAD2L1 is a component of the mitotic spindle assembly checkpoint and has been reported to be linked to various types of cancers, such as rhabdomyosarcoma and gastric cancer." (PMID 34603487, 2021). "The expression of miR-30a-3p inhibits small cell lung cancer cell proliferation, induces cell cycle arrest, and apoptosis, potentially through targeting DONSON, and regulates gastric cancer cell proliferation by targeting MAD2L1." (PMID 41361055, 2025). "In addition, abnormal expression of MAD2L1 has also been found in malignant tumors such as multiple myeloma, gastric cancer, and ovarian serous adenocarcinoma." (PMID 35305591, 2022). "Furthermore, MAD2L1 has been reported in glioblastoma as a target of tumor suppressors, including miR-30a-3p, which inhibited the proliferation of gastric cancer cells." (PMID 35132379, 2022). "Interestingly, MAD2L1 was reported to be regulated by miR-30a-3p in the proliferation of gastric cancer cells." (PMID 34307169, 2021).